CD4 (CD4 molecule)
Diseases named in the same sentence as CD4 in open-access papers (continued):
Sharing a sentence is not in itself a finding about the gene and the disease.
Skin rash (17 papers, 2005 to 2025). A red eruption of the skin. "In EFV group, developing skin rashes was associated with older age (P = 0.02) and baseline CD4 cell count≧350 cells/μl (P = 0.004) in univariate analysis (data not shown)." (PMID 28222098, 2017). "In a multivariate model, use of NVP (adjusted HR 1.67, 95% CI 1.28–2.10), female gender (aHR 1.39, 95% CI 1.01–1.92), and CD4 counts (aHR 0.88, 95% CI 0.82–0.95, for each 50 cells/mm3 increment in baseline CD4) were associated with risk for developing a rash." (PMID 24728406, 2014). "The risk factors identified in association with skin rash on adjusted analysis included nevirapine use, female gender and low baseline CD4 counts." (PMID 24728406, 2014). "In summary this study has shown that in Ghana, in contrast to the findings of other studies outside Africa, a low baseline CD4 count is risk factor for developing a NNRTI-related rash in patients starting ART." (PMID 24728406, 2014). "In multivariate analysis developing a rash was associated with nevirapine use (aHR 1.67, 95% CI 1.28–2.10), female gender (aHR of 1.39, 95% CI 1.01–1.92) and lower baseline CD4 counts (aHR 0.88, 95% CI 0.82–0.95 per 50 cells/mm3 increment)." (PMID 24728406, 2014). "A strong association between grade ≥2 rash and nevirapine-based treatment was observed when only subjects with CD4+ >250 cells/mm3 were considered (P = 0.001), suggesting an interaction between the treatment and the CD4+ count." (PMID 22506127, 2012). "Pregnant subjects with baseline CD4+ >250 cells/mm3 were significantly at risk of developing grade ≥2 rash (P = 0.042)." (PMID 22506127, 2012). "The effects of high baseline CD4 counts on risk of NVP-induced rash were reportedly observed mainly in patients whose CD4 counts were over 250 cells/μl." (PMID 19845952, 2009). "Previous studies have also suggested that higher CD4 counts at baseline increased risk of NVP-induced rash." (PMID 19845952, 2009). "Moreover, in the present study, PD-1 expression was substantially upregulated in the effector memory CD8+ T cells of ABC-fed B*57:01-Tg mice as well as their CD4+ T cell-depleted counterparts; this might suppress the induction of skin rash often associated with clinical AHS." (PMID 34584206, 2021). "In multiple logistic regression analysis, only baseline CD4 cell count ≧350 cells/μl (AOR, 2.326; 95% CI, 1.211–4.466) was independently associated with the development of skin rashes." (PMID 28222098, 2017). "On the other hand, a higher baseline CD4 cell count and use of NVP plus 2 NRTIs were independently associated with the development of skin rashes." (PMID 28222098, 2017). "A profound increase in CD4 counts during the initial phase of treatment has been proposed as one of the possible explanations for the development of NNRTI-related skin rash." (PMID 24728406, 2014). "This is a somewhat different result from those of previous studies and implies that we cannot use rash distribution or severity as an indicator of CD4 count." (PMID 24004854, 2013). "When we picked up patients whose baseline CD4 were less than 100 cells/μl, HLA-Cw*04 allele frequency was 0.2045 in 22 NVP-induced rash cases and 0.0897 in 39 NVP-tolerant patients." (PMID 19845952, 2009). "The medians of CD4 cell counts of NVP-induced rash and NVP-tolerant group were comparable at both time points of immediately before NVP treatment and 6 month after treatment." (PMID 19845952, 2009). "When we picked up patients whose baseline CD4 counts were over 100 cells/μl, HLA-Cw*04 allele frequency was 0.25 in 14 NVP-induced rash cases and 0.025 in 20 NVP-tolerant patients." (PMID 19845952, 2009). "In our study, however, the median baseline CD4 counts of NVP-induced rash cases (43.5 cells/μl) was very similar to that of 248 NVP-tolerant patients (43 cells/μl)." (PMID 19845952, 2009). "As the previous studies have demonstrated that persons with a higher baseline CD4 cell counts are likely to develop rash from NVP." (PMID 16120209, 2005).
Skin rash (continued). "Because the majority of patients taking ABC are HIV-positive and thus have a low CD4+ T cell count, we initially examined whether depleting CD4+ T cells, including Treg, caused ABC-induced skin rash in B*57:01-Tg mice." (PMID 34584206, 2021). "In univariate analysis in NVP group (data not shown), we found that baseline CD4 cell count (P = 0.002), HBsAg positivity (P = 0.04) and development of skin rash within 4 weeks of cART (P<0.001) were associated with hepatotoxicity of grade 2 or greater." (PMID 28222098, 2017). "In addition, a higher baseline CD4 count and use of NVP were associated with the development of skin rashes." (PMID 28222098, 2017). "In Kaplan Meier survival analyses, the use of nevirapine (rather than efavirenz), more advanced WHO stage and lower CD4 counts at baseline were all associated with an increased risk of developing a rash." (PMID 24728406, 2014). "Increasing rash severity was associated with lower CD4 cell counts, but this trend was not statistically significant (p=0.7)." (PMID 24004854, 2013). "Older age (P < 0.003) and a higher CD4+ cell count (P < 0.03) were predictors of rash development." (PMID 22506127, 2012). "For example, other than the CD4 count cut-offs that are associated with risks for hepatotoxicity related of NVP, we previously found that elevated aminotransferase values at baseline were associated with NVP-associated skin rashes in HIV-positive patients in Taiwan." (PMID 28222098, 2017). "Indeed in our cohort, a lower CD4 T-cell count at the time of initiating therapy followed by a more profound recovery in CD4 counts measured within 6 and 12 months were factors associated with a NNRTI-related skin rash." (PMID 24728406, 2014). "Furthermore, no factors (i.e., gender and CD4 cell counts) were associated with skin rashes in the present study according to the results of logistic regression analysis (data not shown)." (PMID 17352834, 2007). "CD4 Treg, CD8 naive T, CD8 Teff, ISGhi T, ISGhi Mo, C1QChi Mφ, ISGhi CECs and AECs showed positive correlations with various skin rashes (heliotrope rash, Gottron's papules, V sign, shawl sign and holster sign)." (PMID 40874258, 2025). "Within HIV negative DRESS patients, there was a positive correlation between dermal CD4+FoxP3+ T-cells with days from symptoms onset to sampling (p = 0.02), eosinophils count (p = 0.006), and BSA skin rash (p = 0.01)." (PMID 37215719, 2023). "In multiple logistic regression analysis, a higher baseline CD4 cell count (per 100-cell/μl increase, AOR, 1.705; 95% CI, 1.187–2.449) and development of skin rashes (AOR, 4.704; 95% CI, 1.537–14.394) were independently associated with the development of hepatotoxicity." (PMID 28222098, 2017). "Although skin rash resolved significantly with this treatment, we hope that expanded NK cells may also act to maintain the confinement of the HTLV-1-positive CD4+ cells in the skin and prevent the progression from IDH to the HAM/TSP stage of the disease." (PMID 25431695, 2014). "Gender, body weight, baseline CD4 cell counts, or receiving fluconazole were not predictive of skin rashes." (PMID 16120209, 2005). "Thus compared with those who had no skin rash, patients who developed a NNRTI-related skin rash had more profound increases in CD4 counts from baseline." (PMID 24728406, 2014).
Abdominal obesity (16 papers, 2015 to 2026). Excessive fat around the stomach and abdomen. "Among the PLHIV, CD4 count below 350 cells/μL as compared to higher levels, and higher viral load by a trend, were associated with lower likelihood of having abdominal obesity in univariable analyses." (PMID 37507703, 2023). "The present study also revealed that sex, occupational status, type of ART regimen, current CD4 counts, BMI, and abnormal blood pressure were associated with central obesity." (PMID 34504719, 2021). "Different factors were implicated for central obesity such as female gender, advanced age (age of 40–49 years and ≥50 years), higher CD4+ lymphocyte count (>350 cells/mm3), higher fasting plasma glucose, and higher body mass index (BMI)." (PMID 34504719, 2021). "After adjusting for potential confounders by logistic regression, sex, occupational status, type of ART regimen, current CD4 counts, BMI, and abnormal blood pressure were associated with central obesity." (PMID 34504719, 2021). "Since females appear to be at greater risk, we also determined the potential relationship between central obesity and CD4 T-cell counts." (PMID 25887844, 2015). "The proposed association between central obesity (W:H ratio) and CD4 can be explained by leptin (secreted by adipocytes) aiding in the proliferation of CD4+ T-cells." (PMID 25887844, 2015). "Risk factors significantly associated with high HOMA-IR included older age, BMI ≥ 25, abdominal obesity, waist circumference, use of thymidine analogues and/or didanosine, time with HIV, and CD4+ nadir < 200 cells/μL." (PMID 35643429, 2022). "Being female, increased BMI, low CD4 count, AZT + 3TC + EFV, ABC + 3TC + ATV/r-based regimen, and abnormal blood pressure were associated with central obesity." (PMID 34504719, 2021). "In this study, a higher CD4 count increased the odds of central obesity." (PMID 34504719, 2021). "Therefore, this study aimed to test the hypothesis that central obesity and cardiorespiratory fitness influence the anti‐inflammatory function of CD4+ T cells differentiated into Tregs in an mTOR pathway‐dependent manner in young adult males and females." (PMID 40853927, 2025). "it was detected that both children with central obesity and children with long-term diabetes type 1 (DM1) have elevated levels of CD4+CD161+CD196+IL-17+ cells in the peripheral blood." (PMID 35873001, 2022). "Moreover, the odds of central obesity were decreased by 97% (AOR: 0.03; 95% CI: 0.007, 0.160) among participants who had a CD4 count <200 cells/mm3 compared to respondents who had a CD4 count >500 cells/mm3." (PMID 34504719, 2021). "The mean BMI, prevalence of BMI-defined overweight, duration of HIV infection and the mean CD4 cell count were higher in the HAART group than in the HAART-naïve group, while the mean WHR and the prevalence of WHR-defined abdominal obesity were similar in both groups." (PMID 27195956, 2016). "Abdominal obesity, identified by an increase in waist-hip ratio (WHR), was associated with higher triglycerides values independent of CD4 count." (PMID 26986065, 2016). "However, a systematic review showed that central obesity is evident among patients with CD4 counts <350 cells/mm3 but not among patients with higher CD4 counts." (PMID 34504719, 2021).
alopecia areata (16 papers, 2010 to 2025). Loss of scalp and body hair involving microscopically inflammatory patchy areas. "Clinically, patients can be presented with patchy, diffuse, or total body hair loss.The pathogenesis of alopecia areata is still unclear, however, there is accumulating evidence hypothesized that alternation in CD4, CD8 T cells and their cytokines are the main inducers of hair loss." (PMID 35300587, 2022). "T-lymphocytes CD4+ Th17 and Treg are also involved in the pathogenesis of alopecia areata, as Th17 infiltrates the dermis and around the hair follicle (T-cells CD4+ were abundant after upregulation of MHC class II molecules in the hair follicle)." (PMID 36292745, 2022). "The most characteristic histopathological change in alopecia areata is hair bulbs that are surrounded by bulbar lymphocytes, which are composed of both CD4+ and CD8+ T cells." (PMID 30886861, 2019). "It is commonly used to treat mild to moderate alopecia areata, because it effectively inhibits CD4+ and CD8+ cells and their cytokine generation." (PMID 27464024, 2016). "The immune mechanism of alopecia areata is reflected in the release of autoantigen from melanocytes, removal of immune privilege, and the abnormal CD4+ and CD25+ T cells." (PMID 24204391, 2013). "It is commonly used to treat mild to moderate alopecia areata, due to the function of inhibiting the CD4+ and CD8+ T cells and the cytokine generated by CD4+ and CD8+ T cells, with good efficacy." (PMID 24204391, 2013). "IFN-γ is the main cytokine known to be aberrantly expressed in alopecia areata through a CD4+ Th1 mediated response." (PMID 20300578, 2010). "Another study described that the active disease stage of alopecia areata was connected with a decrease in the number of circulating CD4, CD8 and NK T cells and an increase in the CD4/CD8 T cell ratio; however, the levels of these cells were higher with increasing disease duration." (PMID 38892934, 2024). "PBMC from patients with progressive alopecia areata reveal a higher percentage of CD4+ CD25+ CD154+ T-cells that suppress the proliferative activity of CD8+ PBMC to a much lesser extent when compared with CD4+ CD25+ PBMC of health donors or patients with stable or regressive alopecia areata." (PMID 20300578, 2010). "It is commonly used to treat mild to moderate alopecia areata, due to the function of inhibiting the CD4 and CD8T cells and the cytokine generated by CD4 and CD8T cells." (PMID 39902296, 2024). "Many studies have shown that inflammatory immune cells, such as CD4+ and CD8+ T cells, lead to dystrophic hair follicle cycling with premature entry into the telogen phase in alopecia areata-affected mice or human models." (PMID 32984299, 2020). "In particular, it is considered that the population of CD4+ CD25+ CD154+ PBMC that express CD44v7+ is very resistant to apoptosis and characterizes active alopecia areata." (PMID 20300578, 2010). "People with alopecia areata (AA) have increased proportions of circulating CCR6+ “Th17” and CXCR3+CCR6+ “Th1/17” CD4 T cells, which are elevated significantly more often in individuals with <50% hair loss, indicating that the early stages of the disease may be more immunologically active." (PMID 36200950, 2022).
autoimmune lymphoproliferative syndrome (16 papers, 2007 to 2025). Autoimmune lymphoproliferative syndrome (ALPS) is a rare, inherited disorder characterized by non-malignant lymphoproliferation, multilineage cytopenias, and a lifelong increased risk of Hodgkin's and non-Hodgkin's lymphoma. "These loss-of-function RasGRP1 mutants lead to the development of autoimmune lymphoproliferative syndrome (ALPS), CD4+ T cell lymphopenia, recurrent infections, hepatosplenomegaly, and lymphadenopathy." (PMID 36675167, 2023). "Patients with autoimmune lymphoproliferative syndrome (ALPS) and lymphoproliferation (LPR) mice are deficient in Fas, and accumulate large numbers of αβ-TCR+, CD4−, CD8− double negative (DN) T cells." (PMID 23762329, 2013). "CD3+/TCRαβ+ CD4-/CD8- ‘double negative’ (DN) T-cells were 0.25 %, making a diagnosis of autoimmune lymphoproliferative syndrome (ALPS) less likely." (PMID 33472608, 2021). "Another example is autoimmune lymphoproliferative syndrome (ALPS), which is mainly characterised by the proliferation of CD4-/CD8- double negative lymphocytes." (PMID 30060490, 2018). "However, some studies have identified a very rare subpopulation of T cells which express the TCRα/β but do not express CD4 or CD8 (TCRα/β CD4−CD8−) in lpr/lpr mice and can induce autoimmune lymphoproliferative syndrome (ALPS)." (PMID 29250557, 2017). "Autoimmune lymphoproliferative syndrome (ALPS) is an inborn error of immunity (IEI) characterized by abnormal FAS-mediated apoptosis of lymphocytes that leads to lymphoproliferation and expansion of CD4−/CD8− double-negative T cells (DNTs)." (PMID 41608120, 2025).
B cell deficiency (16 papers, 2011 to 2026). A broad classification of disorders where circulating numbers of B lymphocytes are decreased or ineffective. "Patients with B-cell deficiency also showed concurrent reductions in total T cells, CD4+ T cells, and CD4+CD25+CD127low/FOXP3+ regulatory T cells (Tregs)." (PMID 41141591, 2025). "Regarding the lymphocyte subpopulations, she presented a B-cell deficiency with increased autoreactive B-cells and a CD4+ and Treg deficiency." (PMID 36465938, 2022). "B cell deficiency in μMT-ApoE−/− mice not only completely abolished total immunoglobulin production but also significantly reduced activated CD4 T cells." (PMID 31998318, 2019). "In keeping with these observations, B cell deficiency also enhanced CD4+ CTL differentiation in this study." (PMID 27806296, 2016). "Several murine experimental models have demonstrated that B cell deficiency results in failure to prime CD4+ T cells." (PMID 23991203, 2013). "During T. cruzi infection, B cell deficiency results in CD4+ T cells acquiring an unconventional profile that may be pathogenic." (PMID 29209313, 2017). "A relative B-cell deficiency was not confirmed by the total counts, however, the deficiency in CD4+ T-cells remained evident." (PMID 37426653, 2023). "In hyperlipidemic μMT−/− ApoE−/− mice, B cell deficiency decreased atherosclerotic lesions, accompanied by absence of immunoglobulins and reduced CD4 T cell accumulation in lesions." (PMID 31998318, 2019).
Behcet disease (16 papers, 2010 to 2025). A chronic, relapsing, multisystemic vasculitis characterized by mucocutaneous lesions, as well as articular, vascular, ocular and central nervous system manifestations. "SAA-stimulated monocytes from patients with Behcet’s disease were capable of promoting Th17 from peripheral CD4+ T cells." (PMID 31100086, 2019). "As CD4+T cells play a critical role in the pathogenesis of Behcet's disease, we next investigated whether FICZ and ITE were able to influence the development of Th1 and Th17 cells." (PMID 25045206, 2014). "However, Behcet’s disease is most common in patients of Japanese, Middle-Eastern, or Mediterranean origin, history of oral aphthous ulcers, genital ulcers, or skin lesions (HLA B-51, CD4+, CD8+)." (PMID 29450371, 2017). "Memory CD45RO+ T cells from peripheral blood mononuclear cells (PBMCs) of patients with active Behçet disease (BD) and SLE and healthy controls were stimulated with IFNα, showing an elevated expression of IFNγ in memory CD4+ T cells in BD patients and controls, but not in SLE patients." (PMID 38164134, 2023).